LEP (leptin)
Diseases named in the same sentence as LEP in open-access papers (continued):
Sharing a sentence is not in itself a finding about the gene and the disease.
ischemia (15 papers, 2012 to 2025). A hypoperfusion of the BLOOD through an organ or tissue caused by a PATHOLOGIC CONSTRICTION or obstruction of its BLOOD VESSELS, or an absence of BLOOD CIRCULATION. "Also, as leptin can promote angiogenesis, and the αMUPA myocardium showed decreased area at risk 24h post-ischemia, we cannot exclude angiogenesis as one leptin-induced cardioprotective benefit." (PMID 26673217, 2015). "The results suggest that leptin can alleviate ischemia-reperfusion injury in isolated rat heart and improve the systolic function of damaged myocardium." (PMID 35308138, 2022). "The finding that ischemia induces the expression of the murine Lepr in resident vascular cells suggests favourable environmental conditions to the angiogenic action of LEP-expressing APCs." (PMID 28710369, 2017). "The decreased level of serum leptin in HBOT group was possibly because of counteracting effect of ischemia insult against HBOT." (PMID 23510433, 2013). "Leptin can increase ischemia-related ventricular arrhythmias via sympathetic nerve activation." (PMID 35742928, 2022). "One of the pathophysiological mechanisms of this phenomenon is the ability of leptin to modulate the cell signaling pathways involved in the insulin, carbohydrate, lipid and energy metabolisms, resulting in increased myocardial injury during ischemia." (PMID 26989445, 2016). "However, in the 4-hour ischemia group, the level of leptin decreased in all groups." (PMID 40729334, 2025). "We examined the ischemia‐related changes in total ROS generation in the ischemic core and penumbral regions at 6 hr after permanent MCAO to determine whether leptin reduced the oxidative stress induced by ischemic injury in rats." (PMID 30632310, 2019). "Collectively, these findings indicate that, within the studied range, neither the choice of cardioplegic solution nor the duration of ischemia had a statistically significant impact on the myocardial release of IL-4, IL-6, IL-10, leptin, TNF-α following ischemia/reperfusion injury." (PMID 40729334, 2025).
gastritis (14 papers, 2014 to 2025). Inflammation of the stomach. "Plasma ghrelin levels decreased after H. pylori eradication in both peptic ulcer and gastritis patients, while plasma leptin levels increased only in peptic ulcer patients." (PMID 27716077, 2016). "(ii) Plasma active and desacyl ghrelin levels decreased after H. pylori eradication in both peptic ulcer and gastritis patients, while plasma leptin levels increased only in peptic ulcer patients." (PMID 27716077, 2016). "Remarkably, in the present study, both ghrelin and leptin levels before/after H.pylori eradication were measured in relation to peptic ulcer and gastritis." (PMID 27716077, 2016). "LEP plasma level is differentially abundant between patients with gastritis or preneoplasia vs. healthy individuals, and patients with preneoplasia vs. those with gastritis or GC." (PMID 41155404, 2025). "Gastritis induced by HP infection could affect the secretion of gastric-related hormones such as leptin, ghrelin, gastrin and somatostatin, which might influence a predisposition to DM." (PMID 30779804, 2019). "The other one; H. pylori-induced gastritis can potentially affect the secretion of gastric hormones, including leptin, ghrelin, gastrin, and somatostatin, which could affect insulin sensitivity and glucose homeostasis." (PMID 27148410, 2016). "When examining proteins correlated with the third component separating gastritis and preneoplasia, Capping Actin Protein of Muscle Z-Line Subunit a (CAPZA1), a-L-Fucosidase 2 (FUCA2), Endoplasmic Reticulum Aminopeptidase 2 (ERAP2), and LEP are found." (PMID 41155404, 2025). "In the case of gastritis patients, there was a significant decrease in ghrelin levels in eradicated patients, while no changes were found in leptin levels." (PMID 27716077, 2016).
hyperthyroidism (14 papers, 2009 to 2025). Overactivity of the thyroid gland resulting in overproduction of thyroid hormone and increased metabolic rate. "Hyperthyroidism was associated with lower body fat, but, intriguingly, leptin levels were actually found to be higher in the thyrotoxicosis state." (PMID 35929907, 2022). "Likewise, in humans, zinc deficiency has been linked to low leptin levels and, in turn, hyperthyroidism; in fact, some studies have shown that low leptin levels are associated with hyperthyroidism (GBD) and that these levels tend to normalize once the hyperthyroidism is controlled." (PMID 39337701, 2024). "While FGF21 and leptin showed a decrease, ghrelin showed an increase with treatment of the hyperthyroidism." (PMID 35929907, 2022). "The aim of this study was to assess the effect of hyperthyroidism and its treatment on body weight and composition, insulin resistance, and mediators of appetite and energy homeostasis, namely ghrelin, leptin, adiponectin, and FGF21." (PMID 35929907, 2022). "Recently, researchers demonstrate that apart from abnormal circulating levels of TH and thyroid-stimulating hormone (TSH), changes in profile of adipokines (like adiponectin, leptin and resistin, etc.)also have been found in patients with hyperthyroidism." (PMID 30670019, 2019). "In contrast, leptin gene expression in rat epididymal fat is downregulated after experimental hyperthyroidism, although lower circulating leptin levels in response to high thyroid hormone exposure are at least in part attributable to a decrease in body fat." (PMID 28077136, 2017). "This indicates that hyperthyroidism may alter the regulatory mechanisms of leptin in energy metabolism and exercise adaptation." (PMID 41355999, 2025). "Leptin, which is an anorexigenic hormone released from adipose tissue, has been variously reported to be normal, high, or even low in different studies in patients of hyperthyroidism." (PMID 35929907, 2022). "The aim of this study was to assess the effect of hyperthyroidism and its treatment on body weight and composition, insulin resistance, and mediators of appetite and energy homeostasis, namely ghrelin, leptin, adiponectin, and fibroblast growth factor 21 (FGF21)." (PMID 35929907, 2022). "However, concluding that there is a relationship between zinc deficiency, low leptin levels, and hyperthyroidism is not easy, since the mere presence of hyperthyroidism can induce a decrease in leptin levels." (PMID 39337701, 2024). "Bayesian network analysis in the hyperthyroidism group revealed complex interrelationships among FT3, FT4, TSH, IL-15, leptin, IL-6, and TNF-α, with TSH significant regulating inflammatory responses and SMI potentially influencing pre- and post-exercise glucose levels." (PMID 41355999, 2025). "As refered before, there is striking evidence that TH excess lead to prominent changes in classical adipokines (like adiponectin, leptin and resistin, etc.), we wonder serum ZAG, a novel lipid-mobilizing adipokine, whether changed in hyperthyroidism patients." (PMID 30670019, 2019). "Several studies have shown that neither chronic hyperthyroidism nor acute T3 treatment has affected serum leptin levels." (PMID 24058635, 2013). "Although endogenous hyperthyroidism can lead to higher leptin levels, short-term treatment does not change leptinemia, neither does the induction of hyperthyroid states in healthy males." (PMID 19889232, 2009).
insomnia (14 papers, 2014 to 2026). A sleep disorder characterized by difficulty in falling asleep and/or remaining asleep. "Its possible mechanism involves the dysregulation of neuroendocrine control of appetite in insomnia, associated with decreased satiety factor leptin and increased hunger-promoting hormone ghrelin." (PMID 39511656, 2024). "While it has been shown that sleep restriction is related to a reduction in leptin levels, an association between insomnia and increased leptin has also been reported." (PMID 37176140, 2023). "Among many molecular factors, orexin-A and leptin have been associated with insomnia." (PMID 24864160, 2014). "Sleep restriction and insomnia can disrupt leptin and ghrelin balance, elevate cortisol levels, and promote systemic inflammation—all of which contribute to increased appetite, reduced energy expenditure, and visceral fat deposition." (PMID 41283272, 2025). "Inflammatory state:Insomnia-(pw8b)-central nervous system-(pw25)-(pw66)-↑ghrelin:leptin-(pw67)-↑insulin resistance-(pw70)-↑angiotensin II-(pw88)-renin-(pw50)-↑TNF-α, IL-6-(pw41)-↑Inflammatory state." (PMID 35252372, 2022). "Hypercoagulability:Insomnia-(pw8b)-central nervous system-(pw25)-(pw66)-↑ghrelin:leptin-(pw67)-↑insulin resistance-(pw72)-↑platelet factors-(pw73)-↑Hypercoagulability." (PMID 35252372, 2022). "Insomnia has shown to directly affect the levels of leptin (decreases) and ghrelin (increases), which are important hormones that regulate appetite." (PMID 35252372, 2022). "Insomnia is a potential factor behind weight gain, an observation that has been explained by altered leptin and ghrelin activity and higher glucose and insulin levels as well as an increased appetite." (PMID 30467691, 2019). "Sleep inefficiency is a common quantitative indicator to evaluate insomnia, and individuals with poor sleep efficiency are more likely to have poor sleep quality, which affects glucose regulation by changing levels of leptin." (PMID 35546663, 2022). "Finally, individuals with insomnia may have abnormal levels hormones such as leptin and ghrelin, which regulate satiety and hunger respectively, thereby disrupting energy balance and impacting glucose metabolism and homeostasis." (PMID 39916567, 2025). "However, the relationship between orexin-A and leptin in insomnia and in insomnia-induced emotion changes is still unknown." (PMID 24864160, 2014). "Short or fragmented sleep, insomnia and hypersomnia—frequently observed across mood states—have been shown to alter HPA axis activity and appetite-regulating hormones such as cortisol, leptin and ghrelin, thereby increasing appetite, promoting weight gain and decreasing insulin sensitivity." (PMID 41590539, 2026). "Since both leptin and acetyl-L-carnitine appear to be decreased in MDD, a negative association with insomnia would support a contribution of insomnia to metabolic changes in MDD." (PMID 37176140, 2023). "In the present study, we demonstrate that WDD may improve insomnia-induced negative emotions by regulating orexin-A and leptin expression." (PMID 24864160, 2014). "WDD treatment has been proven effective in improving SD-induced negative emotions by regulating orexin-A and leptin, an effect that may have a great impact on the treatment of patients with insomnia." (PMID 24864160, 2014).
non-small cell lung carcinoma (14 papers, 2010 to 2024). A group of at least three distinct histological types of lung cancer, including non-small cell squamous cell carcinoma, adenocarcinoma, and large cell carcinoma. "A functional polymorphism in the promoter region of leptin gene is associated with a threefold increased risk of developing non-small cell lung cancer (NSCLC)." (PMID 21040518, 2010). "Leptin produced by CAFs also leads to increased malignancy in non-small-cell lung cancer (NSCLC) cells via MAPK/ERK1/2 and PI3K/AKT signaling pathways in a paracrine manner." (PMID 37686525, 2023). "The expressions of leptin and leptin receptor were significantly higher in non-small-cell lung cancer (NSCLC) tissues than in normal lung tissues." (PMID 33799880, 2021). "Lung tissues both produce and respond to leptin, and leptin is required for proliferation of various non-small cell lung cancer cell lines, at least in part due to activation of downstream Notch and JAK/STAT signalling." (PMID 29089486, 2017). "Therefore, it was inferred that leptin is most likely to affect non-small-cell lung cancer (NSCLC) through an autocrine and paracrine mechanism." (PMID 31119158, 2019). "An observational study revealed that while leptin and adiponectin were not directly implicated in disease alterations in non-small cell lung carcinoma, resistin, functioning as a pro-inflammatory cytokine, might play a role in the pathogenesis of weight loss in NSCLC patients." (PMID 38263093, 2024).
partial lipodystrophy (14 papers, 2013 to 2025). Loss and redistribution of subcutaneous and/or visceral adipose tissue from specific regions of the body. "Recombinant leptin therapy is currently the only dedicated therapy for generalised lipodystrophy but is effective only in some cases of partial lipodystrophy." (PMID 38745956, 2024). "As expected, lower leptin levels were observed in patients with generalised lipodystrophy in comparison with partial lipodystrophy." (PMID 38034001, 2023). "The serum leptin levels, which are strongly correlated with total body fat mass, were very low in patient 1 (4 ng/mL) and similar to those usually reported in partial lipodystrophy, further confirming the lipoatrophic phenotype." (PMID 34342583, 2021). "Acquired partial lipodystrophy has less low leptin levels, and less metabolic derangements, and therefore metreleptin has lower efficacy." (PMID 26987365, 2016). "In an ongoing study at NIH of 55 patients with generalized and partial lipodystrophy, leptin therapy reduced both HBA1c and triglyceride levels." (PMID 23781317, 2013). "Nevertheless, while generalised lipodystrophy is usually characterised by very low or undetectable levels of leptin, patients with partial lipodystrophy, such as FPLD2, may exhibit leptin concentrations ranging from low to normal values." (PMID 36899861, 2023). "Moreover, although responses appear comparable for partial and generalised lipodystrophy, this is highly likely to reflect selection bias in studies of partial lipodystrophy towards those with more severe metabolic complications and lower baseline serum leptin concentrations." (PMID 37794082, 2023).
Cerebral ischemia (13 papers, 2013 to 2024). Restriction of arterial blood supply to the brain associated with insufficient oxygenation to support the metabolic requirements of the tissue. "In the current study, we investigated the association between leptin and mitochondrial oxidative stress after cerebral ischemia." (PMID 30632310, 2019). "Leptin treatment ameliorates ischemic damage in models of oxygen-glucose deprivation in vitro and in animal models of cerebral ischemia." (PMID 38686200, 2024). "Conversely, the activation of the Jak2 signaling pathway is also pivotal in the cerebral ischemia neuroprotective actions of melatonin, resveratrol, leptin, and erythropoietin derivatives." (PMID 34943061, 2021). "Leptin also exhibited neuroprotective effects on cerebral ischemia due to increased P-STAT3, PGC-1α, and matrix metalloproteases (MMPs), and decreased apoptosis in an in vivo study." (PMID 34835960, 2021). "In a mouse model of cerebral ischemia, treatment with leptin decreased the extent of brain injury as the overall infarct volume was attenuated by leptin." (PMID 30386207, 2018). "Leptin acts as an endogenous mediator of neuroprotection during cerebral ischemia and exogenous leptin administration protects against ischemic neuronal injury in vitro and in vivo." (PMID 26629481, 2015). "Exogenous administration of leptin, exerted neuroprotection against ischemia brain injury both in vivo and in vitro." (PMID 23510433, 2013). "In the present study, leptin reduced ROS formation during cerebral ischemia in rats." (PMID 30632310, 2019). "Leptin may reduce ROS production by affecting mitochondrial function in cerebral ischemia." (PMID 30632310, 2019). "Neuroprotection was also demonstrated in a nonhuman primate model of permanent cerebral ischemia, as systemic leptin administration reduced apoptosis, and diminished infarct size." (PMID 35015765, 2022). "In fact, a large body of experimental data suggests that systemic leptin administration is not detrimental, but rather neuroprotective in the context of brain ischemia and IR injury." (PMID 35015765, 2022). "Based on these results, leptin may regulate mitochondrial respiratory chain enzymatic activities via mitochondria‐targeted STAT3 to reduce ROS production and protect brain tissues from mitochondrial oxidative stress during cerebral ischemia." (PMID 30632310, 2019). "Importantly, neither leptin nor PEG-FBP influenced apoptotic signaling in brain ischemia." (PMID 38203830, 2024).
disc degeneration (13 papers, 2013 to 2026). "In conclusion, this study has demonstrated that disc degeneration is associated with elevated leptin expression, and leptin promotes the osteoblastic differentiation and mineralization of lumbar CEP cells." (PMID 29372627, 2018). "Though, even regenerative and proliferative effects of leptin were interpreted in the light of leptin’s “bad reputation”—“leptin-induced cell proliferation might be a fundamental mechanism, underlying disc degeneration”." (PMID 33396484, 2020). "Therefore, altogether these findings indicated that the leptin-induced cell proliferation might be a fundamental mechanism, underlying disc degeneration." (PMID 31027158, 2019). "In conclusion, this study has demonstrated that disc degeneration is correlated with elevated LEP expression, and the mechanism of LEP promoting calcification and ossification is related to the glycolysis process induced by HIF‐1α." (PMID 41474013, 2026). "We hypothesized that the STZ-HFD model, owing to its preservation of leptin signaling and induction of systemic metabolic and inflammatory stress, will more accurately capture the chronic inflammatory milieu associated with T2D-driven disc degeneration than the genetically obese db/db model." (PMID 41047888, 2025). "We constructed a rat model of disc degeneration and found high leptin expression with CEP calcification." (PMID 29372627, 2018). "Different from healthy obese phenotype described as ‘fat and fit’, ectopic fat visceral deposition may lead to mechanical loading and/or local leptin in the disc structure, and eventually disc degeneration." (PMID 32456662, 2020). "It has been reported that leptin can stimulate the proliferation of rat NP cells and human annulus fibrosus cells in vitro, contributing to the formation of cell clusters, which is a mark of disc degeneration." (PMID 25892402, 2015). "Moreover, OCN knockdown was proceeded to investigate whether LEP regulated glycolysis through OCN‐mediated HIF‐1α in vitro in disc degeneration." (PMID 41474013, 2026). "For example, one study demonstrated that leptin promotes catabolic activity in rat NPCs by upregulating the expression of MMP‐1, MMP‐13, ADAMTS4, and ADAMTS5 via activation of the JAK2/STAT3 pathway, suggesting a mechanism contributing to disc degeneration." (PMID 41497807, 2025). "Consequently, leptin can promote calcification of hyaline cartilage in CEP, interfering with nutrient transpor to the disc cells and, thus, lead to disc degeneration." (PMID 31027158, 2019). "We suggest that leptin promotes the osteoblastic differentiation of CEP cells via the MAPK/ERK signal transduction pathway and may be used to investigate the mechanisms of disc degeneration." (PMID 29372627, 2018). "By comparing these models, we were able to address specific questions regarding the contribution of intact leptin signaling to IVD inflammation and identify cytokines that may play mechanistic roles in disc degeneration under conditions of metabolic dysfunction." (PMID 41047888, 2025). "However, the lack of leptin signaling could confound interpretations of disc degeneration, as leptin appears to promote anabolic processes and reduce catabolic activities in IVD cells." (PMID 41047888, 2025).